NPPA (natriuretic peptide A)
Diseases named in the same sentence as NPPA in open-access papers (continued):
Sharing a sentence is not in itself a finding about the gene and the disease.
atrial fibrillation (45 papers, 2009 to 2026). A disorder characterized by an electrocardiographic finding of a supraventricular arrhythmia characterized by the replacement of consistent P waves by rapid oscillations or fibrillatory waves that vary in size, shape and timing and are accompanied by an irregular ventricular response. "Literature data also report that mutations in the NPPA gene are linked to atrial fibrillation and our results confirm that GO terms and NPPA-enriched KEGG pathways are essential in HF." (PMID 34946895, 2021). "Mutations in NPPA are thought to be responsible for the development of atrial fibrillation (arrhythmia)." (PMID 26109061, 2015). "Case summary: We report the case of a 9-year-old girl identified through population genetic screening as a homozygous carrier of the NPPA c.449G>A (p.Arg150Gln) variant who subsequently developed symptomatic paroxysmal atrial fibrillation (AF) at the age of 18." (PMID 41590864, 2026). "Atria-Enriched GJA5, KCNA5 and NPPA, RA-Enriched HCM4, MIR100HG, REC114 and SMAD7 and Ventricles-Enriched KCNJ2, MYH7, PHLDB2, RPL2L and SLC35F1 were associated with atrial fibrillation." (PMID 34088950, 2021). "The higher the level of DNA methylation modification of some important genes (NPPA, NPRA, NPR-C, RASSF1 A) may be more likely to induce atrial fibrillation." (PMID 38765775, 2024).
Stroke (41 papers, 2013 to 2025). Sudden impairment of blood flow to a part of the brain due to occlusion or rupture of an artery to the brain. "We did not establish an association of CYP2D6∗10, CYP2C9∗3, AGTR1 (1166A > C), ACE (I/D), CYP3A5∗3, and NPPA (2238T > C) gene polymorphisms with stroke susceptibility." (PMID 38298191, 2024). "For example, polymorphisms in the NPPA gene including rs5063, rs5065, and rs5067 have been associated with high risks of stroke, and coronary artery disease." (PMID 35586748, 2022). "NPPA mutation has been disclosed to link with familial AF, increasing the risk of AF and stroke (NPPA p.V32M)." (PMID 36303204, 2022). "In particular, the T2238C variant, falling within exon 3 of the gene and causing the synthesis of a peptide carrying two extra arginines, is the most common NPPA variant associated with stroke." (PMID 30781751, 2019). "The NPPA rs5063 was associated with stroke with unadjusted ORs (95%CI; P value) of 0.71 (0.55–0.92; 0.009) for ischemic stroke and 0.44 (0.23–0.84; 0.013) for cerebral hemorrhage respectively." (PMID 25144711, 2014). "Therefore, the association of CYP2D6∗10, CYP2C9∗3, AGTR1 (1166A > C), ACE (I/D), CYP3A5∗3, and NPPA (2238T > C) gene polymorphisms with stroke in hypertensive patients needs further studies." (PMID 38298191, 2024). "Moreover, when translating the experimental findings to human disease, NPPA was confirmed as a risk factor for stroke in the presence of specific variants responsible for either altered gene expression or an altered protein function." (PMID 30781751, 2019). "The physiological function of NPPA variant and the biological pathways of its involvement in stroke are at present unknown." (PMID 25144711, 2014). "This inconsistency on the association between NPPA rs5063 and stroke might be the results of sample size, different study designs or different ethnic groups." (PMID 25144711, 2014). "It is inconsistent concerning the association between NPPA rs5063 and stroke." (PMID 25144711, 2014). "More work is under way for targeting ischemic sites using atrial natriuretic peptide antibody in stroke rats." (PMID 29890780, 2018). "More work is under way for targeting ischemic sites using atrial natriuretic peptide antibody in stroke induced rats." (PMID 29890780, 2018). "It is necessary for future large scale studies to further explain the NPPA and MTHFR variants and stroke subtypes." (PMID 25144711, 2014). "Additionally, the AGTRAP‐PLOD1 locus gene cluster where CLCN6 is localized has been associated with stroke along with other BP regulatory genes such as MTHFR, NPPA, and NPPB." (PMID 35927940, 2022). "Although we did not measure the circulating levels of ANP as the function of NPPA rs5063, the biological role of this variant may have some effect on the biological pathways of its involvement in stroke." (PMID 25144711, 2014).
cardiomyopathy (31 papers, 2010 to 2025). A disease of the heart muscle or myocardium proper. "Among the identified three genes of DCM with HF, NPPA has already been known to involved in cardiomyopathies, while reports on OMD and PRELP are limited." (PMID 36544902, 2022). "We further examined the expression of molecular markers for cardiomyopathy, including natriuretic peptide A (NPPA), natriuretic peptide B (NPPB) and β-myosin heavy chain (β-MHC)." (PMID 34512174, 2021). "NPPA is upregulated in cardiomyopathy and represents the fetal gene program re-induction that is expected for myocardial disease." (PMID 20084101, 2010). "Thus, NPPA regulation in cardiomyopathy likely integrates both stress-induced signaling and HDAC-mediated chromatin regulation, highlighting that HDAC5 inhibition may reinforce endogenous cardioprotective responses." (PMID 41283336, 2025). "MYH6 was downregulated across all three cardiomyopathy groups, while NPPA was upregulated in DCM and HCM but not significantly in PPCM." (PMID 41283336, 2025). "In other words, NPPA, MYL4, and PAM may serve as potential predictors and biomarkers for the diagnosis and prognosis of cardiomyopathy." (PMID 36034815, 2022).
Myocardial fibrosis (28 papers, 2016 to 2025). "On the other hand, through the activation in the myocardiocytes of growth factor β1 and the Smad proteins, which increase transcription of the genes related to atrial natriuretic peptide and the heavy chain of β-myosin, it is capable of promoting left ventricular hypertrophy and myocardial fibrosis." (PMID 41303145, 2025).
Hypervolemia (24 papers, 2014 to 2025). An increase in the amount of intravascular fluid, particularly in the volume of the circulating blood. "Still in these patients, hypervolemia could increase the release of atrial natriuretic peptide and cause enhanced shedding of the endothelial glycocalyx." (PMID 35079044, 2022).
left ventricular hypertrophy (24 papers, 2012 to 2025). Enlargement of the LEFT VENTRICLE of the heart. "There are also only a few reports focused on analyzing the association between NPPA:rs5065 and NPPB:rs198389 polymorphisms with LVM or left ventricular hypertrophy." (PMID 40429712, 2025).
type 2 diabetes (23 papers, 2013 to 2025). "In atrium, we validated a circRNA in NPPA, a gene that was associated with development of type 2 diabetes." (PMID 28842720, 2017). "Since gene variants are inherited randomly and not subject to confounding, we aimed to investigate whether the variant rs5068 within the NPPA locus is associated with incident type 2 diabetes." (PMID 24586593, 2014).
metabolic syndrome (21 papers, 2013 to 2025). A cluster of metabolic risk factors for CARDIOVASCULAR DISEASES and TYPE 2 DIABETES MELLITUS. "Vice versa genetic variants of the ANP or BNP genes (NPPA, NPPB) that result in an increase in circulating levels of NPs have been associated not only with lower blood pressure, but also with protection from the metabolic syndrome in the general population." (PMID 30016962, 2018).
Hyperglycemia (17 papers, 2012 to 2025). An increased concentration of glucose in the blood. "In STEMI-patients, several factors may contribute to glycocalyx damage, that is, ischemia-reperfusion injury, shock, inflammation (TNF-α), hyperglycemia, atrial natriuretic peptide and oxidized low density lipoprotein (LDL)." (PMID 23433357, 2013).
Hyponatremia (17 papers, 2009 to 2025). An abnormally decreased sodium concentration in the blood. "Acute saline injection induced cardiac overload as evidenced by a significant upregulation of brain natriuretic peptide along with a trend towards increased expression of atrial natriuretic peptide and mild hyponatremia." (PMID 34765890, 2021).
dilated cardiomyopathy (16 papers, 2015 to 2025). "Zhu’s study identified NPPA, OMD, and PRELP as biomarkers for dilated cardiomyopathy and HF using random forests." (PMID 41158506, 2025). "For example, decreased MYL2 and MYH6 gene expression coincided with increased RYR2, HCN4, CORIN, NPPA, ERBB2, and MYH7 gene expression in hypertrophic and/or dilated cardiomyopathy." (PMID 32804947, 2020).
preeclampsia (15 papers, 2013 to 2025). Preeclampsia is a hypertensive disorder of pregnancy that is characterized by new-onset hypertension with proteinuria presenting after 20 weeks of gestation, and depending on mild or severe forms may initially present with severe headache, visual disturbances, and hyperreflexia. "Here, we investigated the expression of corin and the gene encoding pro-ANP, NPPA, in human placenta collected from cases of preterm preeclampsia (requiring delivery before 34 weeks completed gestation) and normotensive gestation-matched controls." (PMID 37047162, 2023). "Within the placenta, the mRNA expression of corin and the ANP-encoding gene, natriuretic peptide precursor A (NPPA), did not significantly differ between pregnancies complicated by preterm preeclampsia or gestation-matched normotensive controls." (PMID 37047162, 2023). "Neither corin nor NPPA expression was overtly altered in placentas complicated with preeclampsia, which is consistent with our previous report." (PMID 37047162, 2023).
atherosclerosis (13 papers, 2013 to 2025). A disease characterized by the build-up of fatty material and calcium deposition in the arterial wall resulting in partial or complete occlusion of the arterial lumen. "Polymorphisms within the NPPA gene have been associated with CHD, atherosclerosis, and ischemic stroke, and functional studies have indicated that NPPA promotes diuresis, natriuresis, and vasodilatation, and may thus play fundamental roles in the pathogenesis of CVDs through these mechanisms." (PMID 40076974, 2025). "For example, a polymorphism in the NPPA gene (rs5065) has been associated with CHD, atherosclerosis, and ischemic stroke." (PMID 35586748, 2022).
fibrosis (13 papers, 2013 to 2025). the formation of excess fibrous connective tissue in an organ or tissue in a reparative or reactive process. "In particular, both ANP and B-type natriuretic peptide appear to inhibit cardiac fibrosis by modulating renin-angiotensin-aldosterone system signaling." (PMID 32422879, 2020).
breast carcinoma (11 papers, 2011 to 2025). "Together, our study identified NPPA as a potential prognostic biomarker for breast cancer patients, whose downregulation is associated with an enhanced malignant behavior of breast cancer cells both in vivo and in vitro and identified the transcription regulation of NPPA by MZF1." (PMID 34616853, 2021). "Further, we observed the reduced NPPA in mRNA and protein levels and the knockdown of NPPA result in the enhanced proliferation, migration, and invasion of breast cancer cells both in vivo and in vitro." (PMID 34616853, 2021). "We have identified a 49-gene ECM signature in breast cancer patients and eventually identified NPPA as an independent prognostic marker with the forward stepwise multivariate Cox regression model." (PMID 34616853, 2021). "We established the Cox regression model in breast cancer patients and identified NPPA as an independent prognostic marker." (PMID 34616853, 2021). "Next, we collected the NPPA immunohistochemistry (IHC) staining in the normal and breast cancer tissues from the Human Protein Atlas database and consistently impaired NPPA level were observed in breast tumor tissues." (PMID 34616853, 2021). "And we observed the enhanced proliferation, migration, and invasion potential of breast cancer cells after NPPA depletion." (PMID 34616853, 2021). "Further, we showed NPPA was decreased in breast cancer in the TCGA and GSE65216 databases, especially in the basal group." (PMID 34616853, 2021). "Considering the fact that the biological function of SEMA3B has been proposed, we seek to unveil the function of NPPA in breast cancer." (PMID 34616853, 2021). "Together, we plotted the expression pattern of ECM-related genes in breast cancer patients and identified a novel independent prognostic factor, NPPA, in the breast cancer patients." (PMID 34616853, 2021). "With both bioinformatics and experimental approaches, we established the expression pattern of NPPA and explored its biological function in breast cancer cells." (PMID 34616853, 2021). "Breast cancer patients were further divided into three different groups according to their separate proliferation potential, and the expression level of NPPA was gradually decreased in patients with higher proliferation potential." (PMID 34616853, 2021). "We further tried to explore the transcription modulation of NPPA in breast cancer cells." (PMID 34616853, 2021). "However, the expression of NPPA in breast cancer is based on a computational study and further validation in patients is needed." (PMID 34616853, 2021). "Results showed NPPA knockdown could significantly enhance the migration and the invasion of breast cancer cells." (PMID 34616853, 2021). "The NPPA knockdown with two different shRNAs could significantly enhance the proliferation potential of 4 different breast cancer cells, despite their subtypes or ER status." (PMID 34616853, 2021). "Eventually, we explored the transcription modulation of NPPA in breast cancer cells." (PMID 34616853, 2021). "We eventually identified NPPA as a novel prognostic marker for breast cancer patients." (PMID 34616853, 2021). "Also, NPPA remains a significant prognostic in breast cancer patients stratified by postoperative radiation condition, but not by ER status, PR status, and PAM50 subtypes." (PMID 34616853, 2021). "Together, our findings identified NPPA as a prognostic marker, unveiled the biological function of NPPA, and explored the transcription modulation of NPPA by MZF1, which we believe would expand the horizon for breast cancer treatment." (PMID 34616853, 2021). "The NPPA expression is downregulated in breast cancer patients, independent of the ER status, PR status, stemness score, and immune infiltrating condition." (PMID 34616853, 2021). "However, the function and expression of NPPA in cancer, such as breast cancer, have not been explored." (PMID 34616853, 2021).
ischemic stroke (9 papers, 2014 to 2025). A stroke disorder caused by obstruction of blood flow to the brain, due to thrombotic (local blood clot formation) or embolic (due to a blood clot or other material traveling from another site) event. "In the present study, NPPA rs5063 was associated with cerebral hemorrhage and marginally associated with ischemic stroke." (PMID 25144711, 2014). "This association of NPPA rs5063 with cerebral hemorrhage remained significant under the allelic model after adjusting for multiple testing by FDR whereas the association of NPPA rs5063 with ischemic stroke remained borderline significant (FDR = 0.216)." (PMID 25144711, 2014). "Therefore, further investigation with a greater sample size is required to evaluate the association between NPPA rs5063 and ischemic stroke." (PMID 25144711, 2014). "We applied FDR adjusting for multiple testing, the association of NPPA rs5063 with cerebral hemorrhage remained significant with 0.2 as cutoff value (FDR = 0.126) and with ischemic stroke remained borderline significant (FDR = 0.216)." (PMID 25144711, 2014). "We further analyzed the interaction between NPPA rs5063 and MTHFR rs1801133 with ischemic stroke and cerebral hemorrhage." (PMID 25144711, 2014). "Our study showed that the NPPA rs5063 was significantly associated with cerebral hemorrhage, and the MTHFR rs1801133 was associated with increased risk of cerebral hemorrhage, but not with ischemic stroke in a Chinese population." (PMID 25144711, 2014).
colitis (8 papers, 2022 to 2024). Inflammation of the colon. "Next, we collected clinical samples from people with UC and mice with DSS-induced colitis, and found that the expression levels of ANP, NPR-A, and NPR-C were reduced, demonstrating that the natriuretic peptide axis was involved in the occurrence and development of UC." (PMID 35280696, 2022). "Next, we detected NPPA, NPR-A, and NPR-C expression in the DSS-induced colitis mouse model and people with UC, and found that the mRNA levels corresponding to all three genes were decreased in colonic tissues of the DSS-induced colitis mouse model, and in colonic tissue of people with UC." (PMID 35280696, 2022).
pulmonary congestion (8 papers, 2012 to 2025). "These rats also exhibited left atrial enlargement, pulmonary congestion, and elevated levels of atrial natriuretic peptide and inflammatory marker IL6." (PMID 38169715, 2023).
myocardial ischemia (6 papers, 2013 to 2022). A disorder of cardiac function caused by insufficient blood flow to the muscle tissue of the heart. "In future research, further experimentation can be done to test the influence of LXNX on CRH and NPPA pathway by in vitro and in vivo experiments on mice with myocardial ischemia." (PMID 29867541, 2018).
acute coronary syndrome (5 papers, 2017 to 2025). Signs and symptoms related to acute ischemia of the myocardium secondary to coronary artery disease. "The SNP (rs5065) in NPPA has been associated with cardiovascular disease risk and acute coronary syndrome." (PMID 32171244, 2020). "The high impact stop lost variant (rs5065) in NPPA has been associated with increased acute coronary syndrome and cardiovascular risk." (PMID 32171244, 2020).
Ascites (3 papers, 2016 to 2022). Accumulation of fluid in the peritoneal cavity (between the layers of the peritoneum that lines the abdomen). "Large amounts of diuretics including furosemide, spironolactone, and human atrial natriuretic peptide and albumin administration together with intensive evaluation of intravascular volume are required to control massive ascites." (PMID 32993506, 2020).
Airway obstruction (2 papers, 2024 to 2025). Obstruction of conducting airways of the lung. "Negative intrathoracic pressure during airway obstruction can lead to elevated atrial natriuretic peptide and reduced antidiuretic hormone secretion, resulting in increased nocturnal urine production." (PMID 41283314, 2025).
alcohol dependence (2 papers, 2014 to 2018). Physical and psychological dependence on alcohol. "GATA4 was suggested to regulate atrial natriuretic peptide (ANP, officially known as NPPA) modulating the amygdala’s response to alcohol dependence and is associated with BP." (PMID 29912962, 2018).
carcinoid (2 papers, 2004 to 2022). "Interestingly, some of the peptidergic genes expressed in only minor subpopulations of normal PNECs (e.g. NPW, NPPA, SST, CARTPT) were detected in many carcinoids, whereas the nearly ubiquitous PNEC peptidergic gene CALCA was absent from most carcinoids." (PMID 36469459, 2022).
congenital heart disease (2 papers, 2008 to 2023). A heart disease that is present at birth. "While, we found a new SNP rs56153133 in the NPPA enhancer, and the risk allele G of SNP rs56153133 was correlated with congenital heart disease." (PMID 36745292, 2023).
familial atrial fibrillation (2 papers, 2014 to 2024). An autosomal dominant heart condition that causes disruptions in the heart's normal rhythm. "Recently, this mutation in the NPPA has been found to be associated with higher circulating levels of ANP in salt-sensitive essential hypertension and in familial atrial fibrillation." (PMID 25144711, 2014).